OGT (O-linked N-acetylglucosamine (GlcNAc) transferase)
Diseases named in the same sentence as OGT in open-access papers (continued):
Sharing a sentence is not in itself a finding about the gene and the disease.
cancer (continued). "In a number of cancers, including of B cell origin, increased O-GlcNAcylation and OGT expression promote PI3K/AKT pathway activity and inhibition of OGT decreases AKT phosphorylation and downstream activity." (PMID 34868034, 2021). "OGT is a promising target in various pathologies such as cancer, immune system diseases, or nervous impairment." (PMID 33937202, 2021). "The transcription factors and co-activator described here are a small cross-section representative of transcription factors and co-activators known the be modified by OGT that function in cancer." (PMID 33916244, 2021). "OGT activity itself, however, can support cancer progression, and the challenge is in determining the nature of the substrates, and biological processes are the primary mediators of this crosstalk." (PMID 34660272, 2021). "Inhibition of the NF-κB pathway can enhance the efficacy of cancer treatment and it has recently been reported that OGT is a key regulator of NF-κB activation." (PMID 34681736, 2021). "Agents targeting OGT directly, such as small molecules and bisubstrate inhibitors, were initially ideal potential therapeutic options in the treatment of cancers." (PMID 34771527, 2021). "As high OGT activity is correlated with poor clinical outcomes in cancer patients, OGT is anticipated to be a target molecule for cancer therapies." (PMID 33535386, 2021). "Yes-associated protein (YAP) and c-MYC were selected to further confirm the specific contribution of O-GlcNAc-modified XIAP-dependent OGT degradation in cancer cells because both proteins are potent oncogenic factors and regulated by O-GlcNAc modification." (PMID 32994395, 2020). "Although OGT protein expression is high in cancer cells, little is known about its regulatory mechanisms." (PMID 32994395, 2020). "O-GlcNAc transferase (OGT) is an enzyme that catalyzes the O-GlcNAc modification of nucleocytoplasmic proteins and is highly expressed in many types of cancer." (PMID 32994395, 2020). "To address this, we examined the levels of this modification and its catalyzing enzyme OGT in cancer cell lines Hep3B, Huh7, and HepG2 and compared them to the noncarcinoma hepatocyte cell line AML12." (PMID 33121131, 2020). "O-GlcNAcylation is elevated in many types of cancers, and the OGT plays a critical role in various cancer phenotypes, including metabolic reprogramming." (PMID 33251387, 2020). "Next, the effect of overexpressed XIAP on cancer cell invasion was examined because XIAP-induced OGT degradation decreased Snail1 levels which in turn upregulated E-cadherin expression." (PMID 32994395, 2020). "We examined the relationship between miR-7-5p, a well-known tumor suppressor, and OGT, a notable enzyme involved in anaerobic glycolysis of cancer cells." (PMID 33251387, 2020). "By rebalancing global O-GlcNAcylation profiles or targeting specific O-GlcNAcylated proteins, small molecules targeting OGT have been identified as exhibiting anti-cancer therapeutic potential." (PMID 33194731, 2020). "In particularly, imbalanced levels of OGT and O-GlcNAcylation have been found in various types of cancers." (PMID 33194731, 2020). "These discoveries about XIAP’s unconventional roles in cancer were supported by this study which identified another molecular mechanism for the XIAP-mediated inhibition of cancer cell proliferation and invasion through the degradation of OGT." (PMID 32994395, 2020). "Dysregulations of the O-GlcNAcylation as well as aberrant expression of OGT and/or OGA have been observed in cancer where they are associated with increased cancer cell proliferation and survival, invasiveness, and metastasis." (PMID 33424836, 2020). "High levels of OGT protein and O-GlcNAcylation have a strong effect in determining the characteristics of many types of cancer cells." (PMID 32994395, 2020).
cancer (continued). "An enhanced O-GlcNAcylation level has been reported in various kinds of tumors 8-10 and OGT also has been described to be increased in myriad cancers such as breast, prostate, and ovarian cancer 11-13." (PMID 32863962, 2020). "The stability of p27KIP1 was also increased in human cancer cells in which OGT was knockdown, concomitantly to a significant decrease of proliferation." (PMID 30853938, 2019). "Multiple reports have shown that OGT/O-GlcNAc is involved in the metastatic, angiogenic, and proliferative processes in cancer cells." (PMID 31847126, 2019). "The disruption of O-GlcNAc homeostasis and alteration of the intracellular protein level of OGT is correlated with altered metabolism in cancer cells 14-16." (PMID 31410220, 2019). "When the selective OGT inhibitor ST045849 was applied to MMTV-PyVT cancer cells ordinarily exhibiting hyper-O-GlcNAcylation, the overall levels of protein O-GlcNAcylation became significantly attenuated compared with the untreated control group." (PMID 31645543, 2019). "Earlier studies have detailed the cross-talk between OGT and mTORC1 in cancer cells, showing that de-regulation of either pathway has a similar effect on the other one46–48." (PMID 30952976, 2019). "In comparison with MECs, OGT expression was significantly down-regulated in both primary carcinoma cell lines." (PMID 31645543, 2019). "From these results, we concluded that O-GlcNAcylation is required for the NRF1-dependent proteasome bounce-back response and that OGT inhibition sensitizes cancer cells to proteasome inhibitors by antagonizing NRF1 stabilization." (PMID 29941490, 2018). "In turn, loss of OGT activity and increased AMPK activity reduced cancer cell growth, impaired HIF-1α activation, and increased SIRT1 activity." (PMID 30237786, 2018). "Physiologically, disruption of OGT and OGA function has been implicated in the pathogenesis of several major health problems, such as diabetes, cancer and neurodegenerative diseases." (PMID 30464755, 2018). "Hyper-O-GlcNAcylation and overexpression of OGT have been described in various cancer types, including lung, breast, colon, liver, prostate, and endometrial." (PMID 30453909, 2018). "OGT inhibition was effective at sensitizing cancer cells to a proteasome inhibitor both in culture cells and a xenograft mouse model." (PMID 29941490, 2018). "In these studies, AMPK and OGT seem to have opposite effects on various proteins involved in cancer metabolism, such as the transcriptional regulator hypoxia-inducible factor-1α and the deacetylase sirtuin 1 (SIRT1)." (PMID 30271380, 2018). "We analyzed how cellular function is altered as a cell is under a hyperglycemic condition and upon OGT inhibition through various interventions, these functions, for example, cancer cell proliferation and survival is reduced." (PMID 30515357, 2018). "While the role of such an O-GlcNAcylation in cancer is still under investigation, the aberrant O-GlcNAcylation cycling, as well as the silencing of OGT, have been analyzed either in normal cell physiology or in other human diseases." (PMID 29865240, 2018). "It has been proposed that in cancer cells, OGT alters HIF-1α stability via regulation of α-ketoglutarate levels." (PMID 30125331, 2018). "MAN1A1, the enzyme responsible for the trimming of high-mannose structures in the ER, is a target gene of FOXO3, elucidating the mechanism by which OGT indirectly controls N-glycosylation found at the surface of cancer cells." (PMID 30400201, 2018). "Previous studies showed that OGT regulates many biological processes through O-GlcNAc modification of target proteins and that active O-GlcNAcylation is closely related to cancer malignancy (34, –, 36)." (PMID 29941490, 2018). "Elevated expression of OGT in cancers has been shown to be advantageous for their tumorigenesis and metastasis." (PMID 29941490, 2018). "Recent studies reported that deletion of OGT blocks the growth and proliferation of several types of cancer cells." (PMID 27331873, 2016).
cancer (continued). "Certain functions of OGT are important for the survival of normal cells, and one option to position OGT as a drug-target, is to use low dose of inhibitor and try to identify cancer-cell specific vulnerabilities." (PMID 26824323, 2016). "The expression and catalytic activity of both FAS and O-GlcNAc transferase (OGT) are high in cancer cells but the reciprocal regulation of the two enzymes remains unexplored." (PMID 26835421, 2016). "Herein, we report that OGT silencing diminished proliferation, in vitro cell survival and adhesion of primary and cancer cell lines." (PMID 27252680, 2016). "OGT activity is important for the proliferation of cancer cells, and inhibition of its activity inhibits tumour formation and metastasis." (PMID 26824323, 2016). "An upregulation of FAS and OGT, and consequently an elevated production of fatty acids combined with an increase in the O-GlcNAcylation level are observed in cancer." (PMID 26835421, 2016). "A synergy between unhealthy diet and cancer development is proposed because of the status of OGT’s natural substrate, UDP-GlcNAc, which is positioned at the crossroad of metabolic pathways." (PMID 27252680, 2016). "Along this study, we demonstrated that OGT impacts proliferation and migration of normal as well as cancer colon cells." (PMID 27252680, 2016). "Over 60 papers were published in the past 3 years describing the relationship between O-GlcNAc and cancer, with a substantial portion of them related to the increase of O-GlcNAc and OGT in several types of tumors." (PMID 26161361, 2015). "Among 31 pairs of samples, 20 pairs showed relatively higher level of OGT expression in cancer tissues than in the matched normal tissues." (PMID 26399441, 2015). "Despite the divergent findings regarding levels of OGT and OGA enzymes in cancers, the results of research have confirmed the carcinogenic potential of O-GlcNAc-cycling enzymes in tumor development and progression." (PMID 25315705, 2015). "We used this literature precedent to bridge our work with the findings gathered by Li and others by working within their established methods for OGT’s role in cancer cell sensitivity to glucocorticoid-induced apoptosis." (PMID 26670328, 2015). "A literature review reveals that cancer cells and tissues appear to display overexpression of both, OGT and O-GlcNAc modification in most cases." (PMID 25315705, 2015). "We wanted to determine if inhibition of OGA, by thiamet-G in A549, and CCRF-CEM and CEM-c1 would produce an effect similar to overexpression of OGT, wherein glucocorticoid–resistant cancer cells became less resistant to glucocorticoid induced cell death." (PMID 26670328, 2015). "Because cancer cells appear to overexpress OGT, strategies to reduce OGT activity or expression level are attractive as an anti-cancer approach." (PMID 25426101, 2014). "It should be noted that FoxM1 is a transcription factor that regulates MMP-2 expression, suggesting that OGT regulates cancer cell invasion by modulating MMP-2 expression." (PMID 24918087, 2014). "In many different cancers, O-GlcNAc homeostasis appears to be disrupted with increased OGT protein expression and O-GlcNAc levels." (PMID 25520704, 2014). "This knowledge will accelerate the rational design of OGT inhibitors for anti-cancer drug in the future." (PMID 25426101, 2014). "The results of many studies suggest that increased expression of OGT and hyper-O-GlcNAcylation are the universal features of cancers [for review see Ref." (PMID 25250015, 2014). "High activity of OGT as a result of both high substrate level and gene overexpression favors modification of several key factors involved in cancer metabolism reprograming." (PMID 25250015, 2014).
cancer (continued). "In summary, studies on different types of cancer generally indicate increased expression in O-GlcNAc level and OGT expression." (PMID 23964270, 2013). "O-GlcNAcylation and OGT levels are increased in different cancers (breast, prostate, colon...) and vary during cell cycle progression." (PMID 23964270, 2013). "Thus, OGT demonstrates significant potential as a therapeutic target in both cancers and CVDs, and its inhibitor OSMI exhibits broad biological activity and promising application prospects in basic and preclinical research." (PMID 41394960, 2025). "OGT is the only known enzyme that mediates O-GlcNAcylation of proteins at the Ser or Thr residues, we hypothesized that OGT could serve as an important regulator to regulate cancer cell growth and serve as a biomarker for cancer." (PMID 38168435, 2024). "In this study, we observed that deletion of OGT leads to uncontrolled expansion of DNA damage and induces cytosolic dsDNA accumulation in tumor cells, suggesting that OGT is a promising therapeutic target for cancer treatment." (PMID 38168435, 2024). "A decrease in OGT in cancer cells leads to growth reduction and metastasis." (PMID 38443583, 2024). "CARM1 and OGT expression was higher in cancer tissues than in paracancer tissues." (PMID 39715739, 2024). "In this study, we demonstrate that pharmacological perturbation of the proteasome—like that used in cancer treatment— leads to the increased abundance of OGT and OGA in a ribosome-rich fraction, concurrent with O-GlcNAc modification of core translational and ribosome-associated proteins." (PMID 39395807, 2024). "Notably, OGT-mediated O-GlcNAcylation promotes glucose metabolism in cancer, indicating the potential of OGT inhibitors to serve as novel anticancer treatments." (PMID 39178944, 2024). "We next assessed the potential relevance of OGT in human cancer immunity." (PMID 38168435, 2024). "Together, these data strongly suggest that OGT may play a critical role in tumorigenesis and serve as a prognostic marker and therapeutic target in cancer treatment." (PMID 38168435, 2024). "Importantly, this pathway senses energy levels and links metabolic activity to the regulation of cell proliferation, with clear implications in many cancers where OGT overexpression was also reported." (PMID 39337539, 2024). "The observed elevation of O-GlcNAcylation in cancer cells may be due to the preference of OGT for unstructured and flexible protein regions, which have a higher abundance in cancer compared to normal cells." (PMID 39123480, 2024). "Similar effects were observed in cancer cells treated with si/shRNA targeting OGT." (PMID 39413067, 2024). "Thus, OGT and O-GlcNAc play a positive role in regulation invasion and metastasis in a number of cancers." (PMID 37838167, 2023). "It is likely that OGT and O-GlcNAc play a critical role in maintaining homeostasis in non-cancer cells, and thus targeting OGT with small molecule inhibitors could result in unwanted side effects." (PMID 37838167, 2023). "In xenograft models, the O-GlcNAc–deficient YTHDF1-AFA mutants attenuated tumor progression, suggesting that OGT could regulate many more downstream substrates to promote cancer growth." (PMID 37086786, 2023). "In addition, OGT also directly modifies Rab3A in hepatocarcinoma cells to regulate the metastasis ability of these cancer cells." (PMID 37838167, 2023). "In hypopharyngeal squamous carcinoma, a high level of OGT and O-GlcNAc enhances the stability NF-E2-related factor 2 (NRF2), which is closely associated with survival and chemoresistance of cancer cells, via activation of the PI3K/Akt pathway to drive the tumor growth." (PMID 37838167, 2023). "Likewise, OGT catalyzed O-GlcNAcylation of a variety of transcriptional regulators is fundamentally important in cancer cells." (PMID 37689115, 2023). "Additionally, studies have also shown that OGT and components of the Wnt/β-catenin pathway cooperatively drive cancer cell tumorigenicity." (PMID 37838167, 2023).
cancer (continued). "In cancer cells, inhibition of OGT results in reduced cell proliferation." (PMID 37838167, 2023). "Moreover, cancer cells can even enhance the metabolic flux of the HBP through metabolic reprogramming to increase the availability of OGT substrates." (PMID 36473120, 2023). "To test whether TNBC cancer stem cell populations responded to OGT inhibition, we analyzed the production of stem cell markers in MBA-MB-468 cell lines." (PMID 37231419, 2023). "Interestingly, the substantial increase in OGT levels in cancer cells makes it an effective indicator for cancer monitoring." (PMID 38116061, 2023). "The process of de novo lipid biosynthesis is also controlled by OGT/O-GlcNAc in cancer." (PMID 37838167, 2023). "In these cancer cells, the activity of OGT is controlled by cell migration-inducing and hyaluronan-binding protein (CEMIP), which functions as an adapter protein to facilitate O-GlcNAcylation of β-catenin, which in turn promotes nuclear localization of β-catenin." (PMID 37838167, 2023). "The crucial roles of OGT and O-GlcNAc in promoting cancer cell survival via regulation of pro-survival factors as described in the previous section suggest that OGT and O-GlcNAc also potentially contribute to promoting resistance to anti-cancer therapeutic agents." (PMID 37838167, 2023). "OGT and O-GlcNAc have recently been shown to be involved in developing resistance in cancer cells." (PMID 37838167, 2023). "In a cardiac myocyte study, hyper O-GlcNAcylation increased maximum respiratory capacity and decreased ROS, suggesting that OGT/O-GlcNAcylation could play a similar role in cancer." (PMID 37838167, 2023). "Moreover, many cancers have elevations in OGT expression, and one potential benefit would be to increase aneuploidy." (PMID 37820866, 2023). "Nevertheless, various selective inhibitors of OGT have been developed and tested in cancer cells." (PMID 37838167, 2023). "Both catalytic and non-catalytic functions of OGT are required for mammalian cell proliferation and are associated with cancer-related phenotypes." (PMID 37838167, 2023). "Nevertheless, the potential of using OGT inhibitors in treating cancer should be explored." (PMID 37838167, 2023). "Similarly, OGT inhibition is reported to reduce cancer cell proliferation and metastasis in several types of cancers." (PMID 37689115, 2023). "In cancer cells, OGT and O-GlcNAc couple alteration in nutrient status to signaling activities, which contributes to reprogramming cellular metabolism, as well as to modification of transcriptomic and proteomic profiles, driving the progression of cancer." (PMID 37838167, 2023). "The alteration in cancer cell metabolism is influenced by the availability of nutrients in the tumor microenvironment, which is detected by nutrient-sensing mechanisms, such as OGT and O-GlcNAc." (PMID 37838167, 2023). "Notably, an augmented level of O‐GlcNAcylation is frequently observed in various malignancies, and targeted suppression of OGT has been demonstrated to mitigate cancer growth." (PMID 38034101, 2023). "Core components of the Hippo pathway are regulated by OGT and O-GlcNAc in cancer." (PMID 37838167, 2023). "Interestingly, increases in OGT and O-GlcNAc levels in hepatocarcinoma cells increase the sensitivity of cancer cells to ferroptosis in a Yap-dependent manner." (PMID 37838167, 2023). "Together, these findings begin to reveal the indispensable role of OGT and O-GlcNAc in regulating cancer stem-like cells and phenotypic plasticity, which may also contribute to the regulation of cancer metastasis." (PMID 37838167, 2023). "Overall, increased OGT and O-GlcNAc levels in cancer cells potentially govern a spectrum of cancer-promoting activities through mechanisms that may be cancer-cell or context-specific." (PMID 37838167, 2023). "OGT inhibitors can potentially be used in combination with other chemotherapeutic or targeted therapies to enhance the sensitivity of cancer cells to anti-cancer treatment." (PMID 37838167, 2023).